ZNF827 (zinc finger protein 827)
Description:
As part of a ribonucleoprotein complex composed at least of HNRNPK, HNRNPL and the circular RNA circZNF827 that nucleates the complex on chromatin, may negatively regulate the transcription of genes involved in neuronal differentiation. Could also recruit the nucleosome remodeling and histone deacetylase/NuRD complex to telomeric regions of chromosomes to regulate chromatin remodeling as part of telomere maintenance.
Tractability: PROTAC: UniProt records ubiquitination sites on it; ubiquitination databases record sites on it.
Gene: Protein-coding gene on chromosome 4 (145,757,627 to 145,938,823, reverse strand). Ensembl gene ENSG00000151612.
Subcellular location: Nucleus; Chromosome, telomere
Subcellular location (Human Protein Atlas): Nucleoplasm
Pathways (Reactome):
Chromatin organization: Interaction of NuRD complexes with transcription factors
Gene Ontology:
Molecular function: NuRD complex binding; protein binding; DNA-binding transcription factor activity; transcription cis-regulatory region binding
Biological process: chromatin remodeling; establishment of protein localization to telomere; negative regulation of DNA-templated transcription; negative regulation of shelterin complex assembly; telomere maintenance; regulation of DNA-templated transcription
Cellular component: chromatin; chromosome, telomeric region; ribonucleoprotein complex; nucleoplasm; nucleus
Genetic constraint (gnomAD): Loss-of-function variants: 13 observed, 104.66 expected, observed/expected ratio (o/e) 0.12, 90% interval 0.08 to 0.2. The upper end of that interval is the gene's LOEUF score, 0.2, which puts it in group 1 of 6, group 1 being the genes least tolerant of losing a copy. Missense variants: 1,102 observed, 1,406.4 expected, observed/expected ratio (o/e) 0.78, 90% interval 0.75 to 0.82. Synonymous variants: 522 observed, 562.97 expected, observed/expected ratio (o/e) 0.93, 90% interval 0.86 to 1.
Homologues: Orthologues: chimpanzee ZNF827 (99% identical), macaque ZNF827 (99% identical), dog ZNF827 (96% identical), rabbit ZNF827 (96% identical), pig ZNF827 (95% identical), guinea pig ZNF827 (95% identical), mouse Zfp827 (93% identical), rat Zfp827 (93% identical), tropical clawed frog znf827 (66% identical), zebrafish znf827 (58% identical). Paralogues in human: ZNF142 (12% identical), ZNF574 (10% identical), ZNF208 (9% identical), ZNF107 (9% identical), ZNF91 (9% identical), ZNF184 (9% identical), ZNF526 (9% identical), ZNF84 (9% identical), ZNF569 (9% identical), ZNF160 (8% identical), ZNF729 (8% identical), ZNF282 (8% identical), and 24 more.
Diseases named in the same sentence as ZNF827 in open-access papers:
ZNF827 is named in the same sentence as 11 diseases in open-access papers, as found by Europe PMC text mining. Sharing a sentence is not in itself a finding about the gene and the disease. The quoted sentences say what the papers report.
angina (1 paper, 2025). "Among these sites, cg04425005 in the ZNF827 gene was simultaneously associated with increased risks of MI, CHD, and angina." (PMID 41420191, 2025). "Additionally, cg07091220, also located in the ZNF827 gene, was significantly and positively correlated with the risks of all four CVD: MI, CHD, angina, and HF." (PMID 41420191, 2025).
arterial diseases (1 paper, 2026). "Further investigation using multiple cell types, organoids, and in vivo models may clarify the implications of ZNF827 in arterial fragility observed in SCAD and other arterial diseases." (PMID 41983892, 2026).
cardiomyopathy (1 paper, 2025). A disease of the heart muscle or myocardium proper. "The ZNF827 and the PI3KR2 genes showed a more significant variant burden in controls compared to patients experiencing cardiomyopathy." (PMID 40413218, 2025).
coronary artery disease (1 paper, 2026). "SCAD genetic risk loci, such as the ZNF827 locus on chromosome 4, were previously associated with the risk for coronary artery disease, systolic blood pressure, and ascending aortic diameter variability, but the molecular processes driving these genetic associations are unknown." (PMID 41983892, 2026).
cutaneous melanoma (1 paper, 2019). A primary melanoma arising from atypical melanocytes in the skin. "Our study also proposes genes ESM1, NFATC3, C7orf4, CDK14, ZNF827, and ZSWIM7 as novel putative markers for cutaneous melanoma metastasis." (PMID 31673075, 2019).
Obesity (1 paper, 2023). Accumulation of substantial excess body fat. "Our study also identified several other genes, such as ZNF827, MIR7641-2, RAPTOR, KSR1, GTF3C3, and NFIC, whose role in obesity or obesity-related disorders has been consistently shown in previous studies." (PMID 37204309, 2023). "For example, ZNF827, MIR7641-2, and RAPTOR have been reported to be related to obesity and/or overweight." (PMID 37204309, 2023).
cancer (2 papers, 2024). A tumor composed of atypical neoplastic, often pleomorphic cells that invade other tissues. "Depletion of ZNF827 was shown to impair homologous recombination mediated repair and sensitized cancer cells to treatment with the topoisomerase I inhibitor topotecan, thereby identifying ZNF827 as a potential new therapeutic target." (PMID 39119040, 2024). "Additionally, we demonstrate that ZNF827 depletion inhibits replication initiation and sensitizes cancer cells to the topoisomerase inhibitor topotecan, revealing ZNF827 as a therapeutic target within the DNA damage response pathway." (PMID 38472229, 2024). "ZNF827 depletion sensitizes cancer cells to treatment with the chemotherapeutic topotecan." (PMID 38472229, 2024).
tumor (2 papers, 2017 to 2024). "The resulting facets give us information that shows that three genes HRSP12, INPP4B and ZNF827 contain integrations in both the normal and the tumor samples." (PMID 28969593, 2017). "ZNF827 mediates telomere homeostasis through recruitment of DNA repair proteins, and SATB1 has genome organizing functions in stem cells and tumor progression." (PMID 39545637, 2024).
ZNF827 also shares sentences with these, for which no sentence is quoted: autism (1 paper); depression (1); schizophrenia (1).